TIMP1 (TIMP metallopeptidase inhibitor 1)
Diseases named in the same sentence as TIMP1 in open-access papers (continued):
Sharing a sentence is not in itself a finding about the gene and the disease.
tumor (continued). "On the other hand, TIMP1 serves as an inhibitor of matrix metalloproteinases involved in tissue remodelling and tumour invasion." (PMID 39120548, 2024). "The interaction of proteins with subunits with different TIMP-1 subunits in the inhibitory MMP domain also contributes to tumour growth." (PMID 38956273, 2024). "Further investigation into the differential expression of TIMP1 across immune and tumor regions revealed that heightened TIMP1 expression predominantly occurs in the immune segments of patients with overall high systemic TIMP1 levels." (PMID 38777826, 2024). "Our study seeks to position TIMP-1 as a new immune biomarker for the future development of optimal combinatorial approaches that unleash tumor immunogenicity and ICT benefits." (PMID 38777826, 2024). "Compared with normal samples, the expressions of HSPA1A, HSPB1 and SERPINA1 were down-regulated in tumor samples, while TIMP1 was up-regulated in tumor samples." (PMID 39115879, 2024). "TIMP1 inhibition was shown to suppress LGG cell proliferation, migration, invasion, and the polarization of tumor-associated macrophages." (PMID 39768176, 2024). "TIMP1 promoted the invasive capacity of tumor cells and accelerated tumor progression, which appears to be distinct from the traditional function of MMP inhibitors." (PMID 38638428, 2024). "Overexpression of TIMP-1, -2, and -3 lowers tumor neovascularization and greatly decreases melanoma tumor cell invasion, migration, and metastasis." (PMID 38791873, 2024). "The GEPIA2 analysis results indicate that the top 5 key genes (Bcam, Cdh1, Ifrd1, Mxd1, and Timp1) based on the trajectory analysis of tumor cells can affect the survival of tumor patients." (PMID 38539232, 2024). "This study lays the initial groundwork for further exploration into how TIMP-1 modulates tumor immunogenicity, particularly in light of MHC-I-dependent antigen presentation." (PMID 38777826, 2024). "TIMPs are important inhibitors of MMPs, and TIMP1 is essential for tumor cell proliferation and migration." (PMID 38638428, 2024). "Hypoxia is a key factor in the pathogenesis of gliomas, which enhances tumor development by increasing the expression of stemness (CD133, SOX-2) and drug resistance markers (TIMP-1, Lamp-1) in tumor cells." (PMID 39768176, 2024). "We confirmed a positive correlation between TIMP1 expression and the LYM index, which supported the function of TIMP1 in promoting tumor progression." (PMID 38638428, 2024). "This was consistent with the spatial transcriptome data we analyzed, which showed that MPS with high expression of TIMP1 were distributed more within the tumor, while MPS with high expression of TIMP2 were distributed more in stroma." (PMID 38408082, 2024). "The FAK/PI3K/AKT signaling pathway is reported as a main downstream of TIMP1 and is involved in the pro-tumor effects of TIMP1 in many cancers." (PMID 38770133, 2024). "Subsequently, immunohistochemistry (IHC) staining was performed on the xenograft tumor tissues and revealed that TIMP1 and Ki67 were downregulated in the HHT treatment group." (PMID 38770133, 2024). "Of the 24 tissue sections, proteins encoded by COL4A1, IGFBP3, and TIMP1 were slightly up-regulated in tumor tissues, while GHRL and GJA1 proteins were relatively down-regulated in tumor tissues than para-tumor tissues." (PMID 38273348, 2024). "In particular, these highly expressed genes were notably associated with tumor development and metastatic progression, including A2M, AREG, chemokines (iCAFs-S1), BGN, MFAP5, THBS2, and TIMP1 (iCAFs-S2)." (PMID 39323622, 2024). "HSCs boost the growth of Extracellular matrix (ECM) by producing tissue inhibitor of metal protease 1 (TIMP-1), leading to the creation of a tumor matrix that facilitates tumor cells in evading the immune system." (PMID 38238845, 2024). "Our lower cut-off value segregating prognosis suggests that TIMP1 can exert a more potent impact in limited space like in a tumour microenvironment." (PMID 36768545, 2023).
tumor (continued). "Other KLF4-regulated factors include Ghrelin, TIMP-1 and TIMP-2, ABL, BMI1, Met, GPA33 and Hsp90, which are associated with tumor development and metastasis." (PMID 37031197, 2023). "The methylation levels of CENPA and TIMP1 were downregulated in tumor tissues, while MYCN, in contrast to them, had elevated methylation levels." (PMID 37213288, 2023). "The result of the statistical analysis did not confirm any correlation between the expression of the studied genes (MMP2, MMP9, TIMP1) in blood and tumor tissue." (PMID 37509417, 2023). "Mice receiving the control delivery buffer exhibited relatively larger neoplasms, while those receiving the dCasRx-TIMP1 vector treatment showed smaller neoplasms." (PMID 37735421, 2023). "The results of the statistical analysis showed the impact of the tumor histological subtype on the change in TIMP1 expression during the treatment period (p = 0.035)." (PMID 37509417, 2023). "TIMP-1 is not only a protease inhibitor, but also can promote tumor cell proliferation, survival and induce angiogenesis." (PMID 36690987, 2023). "Apart from the 6–gene score, increased TIMP-1 expression itself has been observed in multiple tumor types in both solid and hematologic malignancies and plays contradictory roles in tumorigenesis." (PMID 36519763, 2023). "As an epithelial cell marker, the role of TIMP1 in the tumor EMT process has been well documented, and it was identified as a biomarker affecting the prognosis of COAD patients." (PMID 36910014, 2023). "BM stromal cells, including mesenchymal cells, are thought to be the source of TIMP1 in the tumour microenvironment." (PMID 36768545, 2023). "The dynamics of TIMP1 levels during the disease course and the positive correlation between TIMP1 protein level and tumour volume in the BM, TIMP1 mRNA levels, and TIMP1 protein levels suggest that MM cells are producers of TIMP1." (PMID 36768545, 2023). "ThyroidPrint® is a novel q-PCR-based ten-gene classifier with its signature representing both the tumor microenvironment (CXCR3, CXCL10, CCR3, CCR7, and CXADR) and tumor epithelial cells (TIMP1, CLDN1, KTR19, AFAPL2, and HMOX1)." (PMID 37671897, 2023). "Another issue raised by our data concerns the biological effect of concomitant TIMP‐1 and CD74 expression and their association in tumor cells." (PMID 37081824, 2023). "In our study, a CRISPR/CasRx-based therapeutic strategy to induce the TIMP1 exon 4–5 exclusion significantly inhibited neoplasm growth in BALB/c nude mice." (PMID 37735421, 2023). "Based on the key regulatory signals in the macrophage-tumor cell regulatory network, we performed a pseudotime analysis of the macrophages and found that signal molecules (TIMP1, VEGFA, SPP1) are highly expressed in immunosuppression-associated macrophages." (PMID 37189418, 2023). "In this context, the endogenous tissue inhibitor of metalloproteinase-1 (TIMP-1) was shown to suppress tumor neovascularization and the angiogenic capacity of endothelial cells." (PMID 37443791, 2023). "TIMP-1 is a multifunctional protein that can promote proliferation, growth, and survival, regulate differentiation, and inhibit apoptosis in several tumor types." (PMID 37014331, 2023). "Wang and Shou have confirmed through detailed in vitro experiments that CENPA and TIMP1 are highly expressed in ccRCC tumor tissues and promote tumor progression through different mechanisms." (PMID 37213288, 2023). "Tissue inhibitor of metalloproteinase-1 (TIMP-1) plays contradictory roles in tumorigenesis, opposing tumor invasion yet promoting cell growth and angiogenesis." (PMID 36519763, 2023). "KLF4 also inhibited the migration and invasion of tumor cells by suppressing biological enzymes, including TIMP-1 and TIMP-2." (PMID 37031197, 2023).
tumor (continued). "In clinical studies, the overexpression of TIMP-1 and TIMP-4 has been associated with a poorer prognosis in many tumours; they activate signalling pathways related to inflammation and fibrosis—for example, mitogen-activated protein kinase (MAPK) pathways." (PMID 38067256, 2023). "And the high level of TIMP-1 is related to the poor prognosis or tumor progression of a variety of malignant tumors." (PMID 36690987, 2023). "Analyzing the correlation between the expression of the TIMP1 gene and the survival depending on a specific histological subtype of the tumor shows the correlation only in adenocarcinoma (p < 0.001)." (PMID 37509417, 2023). "This study confirmed that TIMP1 is a regulator of intercellular interactions among tumor cells, immune cells, and stromal cells and alters the TME to facilitate tumor development." (PMID 37014331, 2023). "Tissue inhibitor of metalloproteinases-1 (TIMP-1) is a secreted protein with a tumor suppressor function due to its anti-proteolytic activity." (PMID 37443843, 2023). "Compared with normal tissues, CENPA expression in tumor tissues was elevated in all three cell types; TIMP1 was elevated in stromal cells and decreased in malignant cells; MYCN expression levels were not significantly different in different cell types." (PMID 37213288, 2023). "Further in vitro and in vivo assays demonstrated that ectopic expression of TIMP1 Δ4-5 significantly suppresses tumor cell growth and metastasis." (PMID 37735421, 2023). "A significant correlation was found between CENPA and TIMP1 expression in tumor tissues and immune cell infiltration, and as expression increased, most immune cell infiltration levels increased." (PMID 37213288, 2023). "Consistent with this, JZL184-mediated dose-dependent tumor regression in A549 xenograft athymic nude mice was associated with decreased numbers of CD31-positive cells and upregulation of TIMP-1-positive cells in xenograft tissue." (PMID 37443791, 2023). "We also evaluated the in vivo effects of TIMP1 Δ4-5 overexpression on tumor growth in a nude mouse xenograft model, which showed that cells overexpressing TIMP1 Δ4-5 generated smaller tumors compared to controls." (PMID 37735421, 2023). "Apart from its inhibitory effect on several matrix metalloproteinases crucial for tumor invasion and metastasis, TIMP1 also plays a vital role in regulating cell populations and exerting anti-apoptotic functions." (PMID 37688768, 2023). "In PCa, the loss of TIMP1 can change the senescence-associated secretory phenotype (SASP) of senescent tumor cells through activation of MMPs, thus promoting tumor metastasis." (PMID 37179366, 2023). "Previously we evaluated that plasma and serum MMP-9, its tissue inhibitor TIMP-1 and classical tumor marker (CEA) levels were significantly higher in GC patients compared with healthy controls." (PMID 37240178, 2023). "siRNAs aimed at suppressing the expression of the Timp1 gene were previously used by researchers in studies related to the development of tumor and pathological processes affecting the connective tissue and extracellular matrix (ECM)." (PMID 36675165, 2023). "TIMP1 can promote tumor cell proliferation, inhibit apoptosis, influence angiogenesis, and facilitate tumor growth and metastasis." (PMID 37497410, 2023). "Significantly higher expression of TIMP1 was observed in tumor tissues compared to normal renal tissues." (PMID 37688768, 2023). "TIMP1 modulates the pericellular proteolysis of a vast range of matrix and cell surface proteins, and affects tumor architecture and cell signaling." (PMID 37014331, 2023). "The publication focuses on the problem of changes in the gene expression of MMP2, MMP9 and tissue inhibitor of metalloproteinases (TIMP1) in the blood of NSCLC patients during therapy (one year after surgical resection of the tumor)." (PMID 37509417, 2023). "CENPA and TIMP1 are highly expressed in the tumor tissue of most cancers, while MYCN is usually lowly expressed." (PMID 37213288, 2023).
tumor (continued). "The results of the analysis showed the presence of correlations between the expression of MMP2, MMP9 and, interestingly, TIMP1 in tumor tissue or blood." (PMID 37509417, 2023). "In the lung-to-lung metastasis mouse model, increased TIMP1 expression accompanied by amiodarone-induced autophagy led to decreased tumor nodules and cancer cell metastasis." (PMID 36457117, 2022). "In serum from animals treated with FLASH at 8 Gy × 2 against subcutaneous tumors, with long-term tumor control, TIMP-1 was significantly lower compared to control animals." (PMID 35853933, 2022). "On analyzing the results, three proteins were found elevated: CXCL16, amphiregulin (a tumor progression protein), and tissue inhibitor metalloproteinases (TIMP1)." (PMID 36358879, 2022). "Using bioinformatics tools and available databases, they demonstrated that EMP3 and TIMP1 are overexpressed in tumor tissue than in control normal brain tissue and that increased expression of these genes is associated with poorer prognosis for patients." (PMID 35454784, 2022). "They demonstrated that TIMP1 played a role in tumor clonogenic survival and vascular density, while TIMP1 inhibition resensitized tumors to gemcitabine and radiotherapy." (PMID 36457117, 2022). "Overall, our data show that TIMP‐1 in hASCs plays a major role in the expression of ECM proteins in tumor spheroids by regulating MMP‐1 activity." (PMID 35600659, 2022). "TIMP-1 and some MMP expression is selectively upregulated in different cancers and strictly associated with tumor malignancy and metastasis." (PMID 35454080, 2022). "The outcomes indicated that TIMP1 expression remarkably correlated with tumor encapsulation and recurrence." (PMID 35778451, 2022). "Tumor spheroids co‐cultured with TIMP‐1‐silenced hASCs showed significantly increased drug efficacy compared to that of the control." (PMID 35600659, 2022). "TIMP1 was prominently localised in the tumour core (TC) of primary tumour tissues, and a high expression of TIMP1 was observed in the invasive margin (IM) of liver MET tissues." (PMID 35140332, 2022). "Tumor-derived tissue inhibitor of metalloproteinases 1 (TIMP-1) was also found to induce liver metastasis via hepatic stromal cell derived factor 1 (SDF-1) and neutrophil recruitment." (PMID 36387238, 2022). "Quantification of TIMP1 in the tumour region of all assessed slides showed a higher TIMP1 expression in the TC of liver MET relative to that in primary CRC tissues." (PMID 35140332, 2022). "In tumor spheroids co‐cultured with TIMP‐1‐silenced hASCs, the activities of MMP‐1 and MMP‐9 were significantly higher than those in the control." (PMID 35600659, 2022). "Intriguingly, MMPs have been found to be synthesized mainly by adjacent and intervening stromal cells, similar to TIMP1 which is secreted in the tumor microenvironment." (PMID 35685428, 2022). "Several studies as well as our IHC data have demonstrated that the overexpression of TIMP1 occurs predominantly at the tumour invasion front in CRC and metastases." (PMID 35140332, 2022). "Tissue inhibitor of metalloproteinase-1 (TIMP-1) is one of the four natural endogenous inhibitors of matrix-degrading enzymes and, therefore, ‘tumor suppressive’." (PMID 36230997, 2022). "Tissue inhibitors of metalloproteinases (TIMPs) are proverbial inhibitors of metalloproteinases and composed of four structurally related members (TIMP1, TIMP2, TIMP3, and TIMP4), associated with tumor invasion and angiogenesis." (PMID 35559040, 2022). "TIMP1 is not only considered a prognostic biomarker for various cancers but promotes tumor progression." (PMID 36146640, 2022). "Secondly, low-dose metronomic scheduling of CDDP is known to block tumor-driven angiogenesis triggering angiostatic mechanisms via modulation of TIMP-1 and different MMPs63–65." (PMID 36075937, 2022).
tumor (continued). "The invasiveness of A549 cells decreased after exposure to CBD, likely due to the upregulation of TIMP-1, an inhibitor of proteases, which enables tumor cells to invade basement membranes and small vessel endothelial cells." (PMID 36437760, 2022). "TIMP1 was found to decrease tumor cell sensitivity to multiple anticancer drugs by activating downstream pathways and it also exhibited anti-apoptotic activity." (PMID 36146640, 2022). "Tumor-derived protein tissue inhibitor of metalloproteinases-1 (TIMP1) correlates with poor prognosis in many cancers." (PMID 36138770, 2022). "At stage I, where the tumor is present, the largest difference in fibroblast signaling to neighboring cells involves increased expression of TIMP1, and collagen isoforms suggesting an early fibroblast activation." (PMID 35565326, 2022). "Increased TIMP-1 expression was reported to correlate with tumor size, metastases, and stage of disease in PTC." (PMID 36551933, 2022). "Consistent with its prognostic significance, TIMP-1 overexpression was shown to promote MDA-MB-231 tumor growth in SCID mice." (PMID 36741729, 2022). "The present study demonstrated the importance of increased glycolytic activity in the tumor-promoting and chemoresistance function of TIMP-1." (PMID 36230997, 2022). "Amongst them, TIMP1 is one of the closest genes correlated with tumor development and immune responses." (PMID 35778451, 2022). "According to the information above, we examined the EMT pathway which was proved to be critical in tumor metastasis by silencing TIMP1." (PMID 35281807, 2022). "Increased level of TIMP1 accompanied by reduced tumor numbers in the Q89L-shGFP group was detected compared to the Vector, Q89L-shATG5, and Q89L-shATG7 groups." (PMID 36457117, 2022). "It has been suggested that TIMP-1 has many roles, including stimulation of cell growth, inhibition of apoptosis and promotion of tumor invasion." (PMID 35853933, 2022). "The higher TIMP-1 saliva concentration was presumably detected due to the shedding of the tumor or the tumor microenvironment with direct contact to the oral and pharyngeal cavity." (PMID 36551979, 2022). "Analysis of the results about correlation between immune infiltrates and TIMP1 expression showed that TIMP1 involved in tumor immunity." (PMID 35685428, 2022). "Our 3D ECM remodelling assays results suggest that elevated TIMP1 levels affect cell dynamics in fibroblasts, which then induce matrix remodelling, subsequently resulting in altered mechanical properties of the tumour microenvironment." (PMID 35140332, 2022). "In conclusion, elevated expression of MMP-1 and TIMP-1 in tumor tissue can predict invasiveness for PTC." (PMID 36551933, 2022). "These proliferative effects depend on soluble PECAM-1 binding to homophilic ligands, which induces endothelial cells to release TIMP metallopeptidase inhibitor-1 (TIMP-1), leading to tumor cell proliferation." (PMID 35884405, 2022). "Analysis through GENE module revealed that TIMP1 expression significantly correlates with tumor purity, the levels of B cells, CD8+ T cells, CD4+ T cells, macrophages, neutrophils, and dendritic cells." (PMID 35778451, 2022). "In our study, a specific positivity for TIMP-1 was seen in tumor samples, which is in agreement with positivity reported in human oral squamous carcinomas." (PMID 36518899, 2022). "TIMP‐1 levels are higher in tumour tissues than in normal tissues and promotes cell growth, tumorigenesis, and angiogenesis." (PMID 35818030, 2022). "The objective of our study was to examine the expression of tumor-progression-associated MMPs (MMP-1, MMP-2, and MMP-9) and tissue inhibitors of metalloproteinases (TIMP-1 and TIMP-2) in locally invasive PTC and their relation to clinicopathological features." (PMID 36551933, 2022).